SET (SET nuclear proto-oncogene)
Description:
Multitasking protein, involved in apoptosis, transcription, nucleosome assembly and histone chaperoning. Isoform 2 anti-apoptotic activity is mediated by inhibition of the GZMA-activated DNase, NME1. In the course of cytotoxic T-lymphocyte (CTL)-induced apoptosis, GZMA cleaves SET, disrupting its binding to NME1 and releasing NME1 inhibition. Isoform 1 and isoform 2 are potent inhibitors of protein phosphatase 2A. Isoform 1 and isoform 2 inhibit EP300/CREBBP and PCAF-mediated acetylation of histones (HAT) and nucleosomes, most probably by masking the accessibility of lysines of histones to the acetylases. The predominant target for inhibition is histone H4. HAT inhibition leads to silencing of HAT-dependent transcription and prevents active demethylation of DNA. Both isoforms stimulate DNA replication of the adenovirus genome complexed with viral core proteins; however, isoform 2 specific activity is higher.
Synonyms: IGAAD; TAF-I; PHAPII; 2PP2A; IPP2A2; TAF-IBETA; I2PP2A; MRD58
Tractability: PROTAC: UniProt records ubiquitination sites on it; ubiquitination databases record sites on it; its protein half-life has been measured.
Gene: Protein-coding gene on chromosome 9 (128,683,424 to 128,696,400, forward strand). Ensembl gene ENSG00000119335.
Subcellular location: Cytoplasm, cytosol; Endoplasmic reticulum; Nucleus, nucleoplasm
Subcellular location (Human Protein Atlas): Nucleoplasm; Lipid droplets
Pathways (Reactome):
Cell Cycle: Condensation of Prophase Chromosomes
Metabolism of RNA: HuR (ELAVL1) binds and stabilizes mRNA
Gene Ontology:
Molecular function: protein binding; histone binding; protein phosphatase inhibitor activity; protein phosphatase regulator activity
Biological process: negative regulation of DNA-templated transcription; negative regulation of neuron apoptotic process; positive regulation of SCF-dependent proteasomal ubiquitin-dependent catabolic process; DNA replication; nucleosome disassembly; nucleosome assembly
Cellular component: cytoplasm; endoplasmic reticulum; lipid droplet; nucleoplasm; nucleus; perinuclear region of cytoplasm; protein-containing complex; chromatin; cytosol
Genetic constraint (gnomAD): Loss-of-function variants: 0 observed, 17.85 expected, observed/expected ratio (o/e) 0, 90% interval 0 to 0.17. The upper end of that interval is the gene's LOEUF score, 0.17, which puts it in group 1 of 6, group 1 being the genes least tolerant of losing a copy. Missense variants: 55 observed, 169.3 expected, observed/expected ratio (o/e) 0.32, 90% interval 0.26 to 0.41. Synonymous variants: 60 observed, 57.89 expected, observed/expected ratio (o/e) 1.04, 90% interval 0.84 to 1.28.
Gene-disease validity (ClinGen):
ClinGen rates the evidence that SET causes each of these diseases.
intellectual disability (autosomal dominant): Definitive.
Cancer hallmarks: escaping programmed cell death (promotes); invasion and metastasis (suppresses); genome instability and mutations (promotes); change of cellular energetics; genome instability and mutations (suppresses); cell replicative immortality (promotes); escaping immune response to cancer (promotes); proliferative signalling (promotes); genome instability and mutations; invasion and metastasis (promotes); escaping immune response to cancer
Homologues: Orthologues: zebrafish setb (93% identical), tropical clawed frog set (88% identical), rat Setl2 (86% identical), dog SET (81% identical). Paralogues in human: SETSIP (88% identical), TSPYL2 (38% identical), NAP1L1 (34% identical), NAP1L4 (34% identical), TSPYL1 (32% identical), TSPYL4 (32% identical), TSPYL5 (32% identical), TSPYL6 (29% identical), TSPY1 (29% identical), TSPY10 (29% identical), TSPY2 (29% identical), TSPY3 (29% identical), and 6 more.
Diseases named in the same sentence as SET in open-access papers:
SET is named in the same sentence as 98 diseases in open-access papers, as found by Europe PMC text mining. Sharing a sentence is not in itself a finding about the gene and the disease. The quoted sentences say what the papers report.
leukemia (33 papers, 2006 to 2025). A malignant (clonal) hematologic disorder, involving hematopoietic stem cells and characterized by the presence of primitive or atypical myeloid or lymphoid cells in the bone marrow and the blood. "The gene encoding for the protein SE translocation (SET) was identified for the first time 30 years ago as part of a chromosomal translocation in a patient affected by leukemia." (PMID 36345878, 2022). "SET protein has been reported to be overexpressed in leukemia and other cancer types and associated with cell proliferation and survival." (PMID 34058077, 2021). "SET is also known as the inhibitor of protein phosphatase 2A (I2PP2A, or the myeloid leukaemia associated oncoprotein SET/TAF-1β)." (PMID 22723854, 2012). "However, the proportion of NOTCH1 mutation seems to be higher in SET-CAN/NUP214 positive leukemia patients." (PMID 37909026, 2023). "In addition, the existence of SET-CAN/NUP214 fusion gene is related to the up-regulation of the expression level of lymphoblastic leukemia-associated hematopoietic regulator 1(LYL1) and myocyte enhancer 2C(MEF2C) genes." (PMID 37909026, 2023). "The mutations of NOTCH1, PHF6 and JAK1 are closely linked in the process of leukemia, which may be the secondary genetic alterations of SET-CAN/NUP214 fusion gene." (PMID 37909026, 2023). "The scope of this review is to summarize the general features and prognostic significance in leukemia associated with the SET-CAN/NUP214 fusion gene and to discuss the methods of detection and treatment, aiming at providing some useful references for relevant researchers in the field of blood tumor." (PMID 37909026, 2023). "Chromatin binding of XPO1 has also been shown in NPM1c and SET::NUP214 leukemia, suggesting that XPO1 mediates and stabilizes chromatin binding of DN." (PMID 40148556, 2025). "H3K4 methylation is catalysed by the evolutionarily conserved SET/COMPASS and MLL (Mixed Lineage Leukaemia) complexes referred to hereafter collectively as the SET/MLL complex." (PMID 40799728, 2025). "Most of these are recurrent and class-defining in pAML (for example, KMT2Ar, 20.3%; RUNX1::RUNX1T1, 12.4%), whereas we also found fusions recurrent in other leukemias, such as SET::NUP214 (n = 1) or SFPQ::ZFP36L2 (n = 1)." (PMID 38212634, 2024). "The data revealed that although SET-CAN/NUP214 fusion gene occurs in various types of leukemia, it mainly occurs in T-ALL." (PMID 37909026, 2023). "In summary, SET-CAN/NUP214 fusion gene is relatively rare in leukemia and mainly occurs in adult male T-ALL patients." (PMID 37909026, 2023). "In this review, we summarized the general features and clinical advances of SET-CAN/NUP214 fusion gene in leukemia." (PMID 37909026, 2023). "Chromosome abnormality involving NUP214 occur repeatedly in leukemia, in addition to the SET-CAN/NUP214 reviewed here, other chromosome abnormalities were found such as DEK-NUP214, SQSTM1-NUP214 and NUP214-ABL1." (PMID 37909026, 2023). "SET nuclear proto-oncogene (I2PP2A) is another potent endogenous PP2A inhibitor that is considered an oncogene in leukemia (AML, CLL & CML), lymphoma, CRC, breast, and lung cancer." (PMID 36358647, 2022). "Aberrant expression of SET has been reported in other cancers such as leukemia, breast cancer, and colon, liver, and lung carcinoma." (PMID 34683924, 2021). "According to previous reports, increased gene expression and protein levels of hnRNP K and SET are frequent events in several types of cancer and they have been proposed to be prognostic markers in leukemia, mainly in CML, increasing during a blast crisis." (PMID 34058077, 2021). "OP449 is a specific, cell-penetrating peptide against SET, which has shown anticancer properties in leukemia, prostate, breast and gastric cancers, but its potential usefulness in CRC remains to be evaluated." (PMID 30871013, 2019). "HOXA gene upregulation has previously been described in SET-NUP 214 leukemia, another NUP214-fusion gene leukemia, through binding to HOXA promoters." (PMID 26436590, 2015).
leukemia (continued). "High levels of SET have been detected in a number of different human malignancies, including cancers from uterus, colon, stomach, and rectum, ovarian tumor, Wilms' tumor and leukemia, thus implying an oncogenic role of SET in tumorigenesis." (PMID 24454695, 2014). "Similar to SET, NPM1 is a nuclear protein that has been implicated in the onset of leukemia and that can shuttle from the nucleus to the cytoplasm and vice versa." (PMID 23874639, 2013). "Further research is needed to evaluate the role of SET-CAN/NUP214 fusion gene in leukemia." (PMID 37909026, 2023). "Furthermore, SET has been found to be de-regulated in some solid tumors and leukemias, and it has been proposed as a novel target for anticancer therapy." (PMID 30871013, 2019). "It is discovered that SET is fused with the nucleoporin NU214 (CAN), and it is associated with myeloid leukemogenesis and highly expressed in Wilms' tumors and BCR-ABL1-positive leukemia." (PMID 24307892, 2013). "SET-CAN/NUP214 fusion gene may contribute to leukemia through direct and indirect effects." (PMID 37909026, 2023). "Consequently, Nucant-mediated occurrence of cell death in leukemia cells might be associated, at least in part, with the functioning of ANP32A and SET." (PMID 21812966, 2011). "In general, the SET-CAN/NUP214 fusion gene is very rare in adult acute leukemia, more frequently found in T-ALL than in other types of leukemia, and more often in males." (PMID 35905214, 2022). "Reactivation of PP2A by SET knockdown or pharmacological treatment with FTY720, increased survival in a mouse model of JAK2V617F leukemia in vivo." (PMID 36345878, 2022). "In another report, the combined knockdown of SET and SET-NUP214 resulted in a reduction of HOXA9 gene expression in a leukemia cell line with endogenous expression of the fusion protein." (PMID 30669574, 2019). "For example, OP449 is a synthetic peptide that binds to SET protein, activates PP2A and selectively inhibits cell growth in leukemia cell lines and primary patient cells." (PMID 28346496, 2017). "SET oncoprotein is an endogenous inhibitor of protein phosphatase 2A (PP2A), and SET-mediated PP2A inhibition is an important regulatory mechanism for promoting cancer initiation and progression of several types of human leukemia disease." (PMID 25945834, 2015). "Of 141 human leukemia/lymphoma cell lines tested, only the T-ALL cell line LOUCY and the AML cell line MEGAL expressed the SET(TAF-Iβ)-NUP214 fusion gene transcript." (PMID 19166587, 2009). "SET-CAN/NUP214 fusion gene is rare in leukemia patients, and there is no prospective clinical study for such patients." (PMID 37909026, 2023). "Therefore, hnRNP K/SET and ERK are potential therapeutic targets for both antineoplastic leukemia therapy and relapsed APL patients with ATRA resistance." (PMID 34058077, 2021). "Genetic (SET shRNA-mediated down-regulation) or pharmacologic restoration (i.e., PADs) of PP2A activity halts malignant cell survival and proliferation both in vitro and in different animal models of leukemia." (PMID 25763353, 2015). "Interestingly, SET (also known as I2PP2A, IGAAD or TAF-Iβ) is a nucleus/cytoplasm-localised phosphoprotein overexpressed in solid tumours and leukaemias." (PMID 16953242, 2006). "This, together with the known function of MLL/SET proteins in embryonic development, has focussed research efforts in recent years on understanding the role of this protein family in developmental haematopoiesis and how this may be subverted by MLL oncofusions in infant leukaemia." (PMID 32389825, 2020). "SET-CAN/NUP214 fusion gene impairs the process of hematopoietic differentiation, but it alone is not sufficient to induce leukemia." (PMID 37909026, 2023). "For example, pharmacologic inhibitors of PP2A negative regulator SET, such as fingolimod, OP449 and its analogs, will likely be ineffective in leukemias without SET overexpression or activation." (PMID 25699237, 2015).
lung cancer (20 papers, 2007 to 2024). A malignant neoplasm involving the lung. "To investigate the functional interplay between SET and ZBTB11 in lung cancer cells, we sought to identify SET-mediated regulation of ZBTB11 direct target genes." (PMID 38355937, 2024). "Taken together, our data characterize ZBTB11 as a binding partner of the oncoprotein SET in lung cancer cells." (PMID 38355937, 2024). "More importantly, this effect on cancer cell migration and invasion by SET depletion was abolished upon concomitant knockdown of ZBTB11, suggesting that SET-mediated metastatic regulation of lung cancer cells is probably dependent on the presence of ZBTB11." (PMID 38355937, 2024). "Recently, it has been shown in a lung cancer model that ceramide can mediate c-Myc degradation by binding I2PP2A/SET, one of the endogenous PP2A inhibitors." (PMID 35159039, 2022). "PP2A has been shown to regulate RhoA in T cells, and Rac1 in lung cancer, implying SET-mediated regulation of PP2A in osteoclasts." (PMID 34884920, 2021). "In fact, the interaction of Pcdh7 with SET, a known oncoprotein that participates in cancer progression, has been shown to play an important role in Pcdh7-induced lung cancer transformation and tumorigenesis." (PMID 34884920, 2021). "We noticed a newly released study in A549 human lung cancer cells identified the inhibitor 2 of PP2A (I2PP2A/SET) as a ceramide-binding protein." (PMID 25050888, 2014). "Knock-down of SET in A549 lung cancer cells produced an increase in PP2A activity and a reduction in tumor proliferation in situ and in SCID mice." (PMID 25642418, 2014). "We then utilized these data to develop a novel strategy for lung cancer treatment via directly targeting I2PP2A/SET, which is highly expressed in these tumour tissues, by FTY720." (PMID 23180565, 2013). "Moreover, the expression of ZBTB11 and SET in lung tissues exhibited a strong correlation, supporting the notion of cooperation between ZBTB11 and SET in promoting lung cancer progression." (PMID 38355937, 2024). "SET has been identified as an oncogene in multiple types of cancers, such as hepatocellular carcinoma, pancreatic cancer, glioblastoma multiforme and lung cancer." (PMID 34774019, 2021). "Importantly, SET protein levels are high in various cancers, including breast, colon, pancreas, gastric, liver and lung cancers." (PMID 34244560, 2021). "Since chemotherapy is one of the major treatments for NSCLC patients in a setting of almost certain eventual chemoresistance, we next investigated whether SET overexpression affects the sensitivity of lung cancer cells to chemotherapy." (PMID 26575017, 2016). "Binding of I2PP2A/SET to ceramide in lung cancer cells might have clinical and biological significance." (PMID 23180565, 2013). "Cutaneous T-cell lymphoma-associated tumor antigen (SE20-4), also known as differentially expressed nucleolar transforming growth factor (TGF)-β1 target protein (DENTT), is a member of the TSPY/TSPY-like/SET/NAP-1 superfamily whose mRNA is overexpressed in TGF-β1-induced human lung cancer cells." (PMID 17938736, 2007). "Therefore, the study of the SET gene in lung cancer cells may lay the foundation as the potential target for the prevention and clinical treatment of lung injury in the future." (PMID 35431948, 2022). "Similar transcriptional regulation of these genes upon SET and/or ZBTB11 knockdown was also recapitulated in H1975 lung cancer cells." (PMID 38355937, 2024). "Previous studies have reported that SET is related to many cellular processes because of its inhibition for PP2A and also acts as an oncogene in HNSCC12 and non‐small cell lung cancer." (PMID 33241617, 2021).
lung cancer (continued). "SET cooperates with ZBTB11 in transcriptional regulation by acting as a cofactor, and the interplay between SET and ZBTB11 is critically involved in modulating the metastatic behaviors of lung cancer cells." (PMID 38355937, 2024). "Overexpression of SET is found in CML, Wilms tumors, and in lung cancers." (PMID 25642418, 2014). "Accordingly, our data elucidates that in lung cancer cells, phosphorylation of FTY720 by SK-2 might be dispensable for I2PP2A/SET targeting, which leads to necroptosis and lung tumour suppression." (PMID 23180565, 2013). "Because I2PP2A/SET was found overexpressed, whereas ceramide was downregulated in lung tumours, a sphingolipid analogue drug, FTY720, was identified to mimick ceramide for binding and targeting I2PP2A/SET, leading to PP2A reactivation, lung cancer cell death, and tumour suppression in vivo." (PMID 23180565, 2013). "In addition, the reduced migration and invasion by knockdown of SET in lung cancer cells was almost completely abrogated upon concomitant ZBTB11 depletion, suggesting that ZBTB11 was one of the major TFs binding by SET to exert SET-involved metastatic regulation in the nucleus." (PMID 38355937, 2024).